COMMD10 (COMM domain containing 10)
Description:
Scaffold protein in the commander complex that is essential for endosomal recycling of transmembrane cargos; the commander complex is composed of the CCC subcomplex and the retriever subcomplex. May modulate activity of cullin-RING E3 ubiquitin ligase (CRL) complexes. May down-regulate activation of NF-kappa-B.
Synonyms: PTD002
Tractability: PROTAC: ubiquitination databases record sites on it; its protein half-life has been measured.
Gene: Protein-coding gene on chromosome 5 (116,085,007 to 116,412,762, forward strand). Ensembl gene ENSG00000145781.
Subcellular location: Cytoplasm; Nucleus
Subcellular location (Human Protein Atlas): Nucleoplasm
Pathways (Reactome):
Metabolism of proteins: Neddylation
Gene Ontology:
Molecular function: protein binding
Biological process: endocytic recycling
Cellular component: cytoplasm; nucleoplasm; nucleus; protein-containing complex; endoplasmic reticulum membrane; endosome membrane
Genetic constraint (gnomAD): Loss-of-function variants: 6 observed, 5.72 expected, observed/expected ratio (o/e) 1.05, 90% interval 0.56 to 1.81. That is too few expected variants to judge how well the gene tolerates losing a copy. Missense variants: 96 observed, 53.26 expected, observed/expected ratio (o/e) 1.8, 90% interval 1.51 to 1.97. Synonymous variants: 32 observed, 19.46 expected, observed/expected ratio (o/e) 1.64, 90% interval 1.22 to 1.95.
Homologues: Orthologues: chimpanzee COMMD10 (99% identical), dog COMMD10 (93% identical), macaque COMMD10 (93% identical), guinea pig COMMD10 (91% identical), mouse Commd10 (89% identical), rat Commd10 (89% identical), pig COMMD10 (81% identical), tropical clawed frog commd10 (75% identical), Drosophila melanogaster Vlet (24% identical).